EOLA2-DT (EOLA2 divergent transcript)
Synonyms: LINC00894
Gene: Long non-coding RNA gene on chromosome X (149,938,613 to 150,224,580, forward strand). Ensembl gene ENSG00000235703.
Diseases named in the same sentence as EOLA2-DT in open-access papers:
EOLA2-DT is named in the same sentence as 11 diseases in open-access papers, as found by Europe PMC text mining. Sharing a sentence is not in itself a finding about the gene and the disease.
EOLA2-DT shares sentences with these, for which no sentence is quoted: cancer (4 papers); breast carcinoma (3); tumor (2); asthma (1); Cerebral ischemia (1); cervical adenocarcinoma (1); follicular thyroid cancer (1); kidney cancer (1); lung carcinoma (1); papillary thyroid cancer (1); thyroid cancer (1).